ERCC1 (ERCC excision repair 1, endonuclease non-catalytic subunit)
Diseases named in the same sentence as ERCC1 in open-access papers (continued):
Sharing a sentence is not in itself a finding about the gene and the disease.
tumor (continued). "Pretreatment immunohistochemical analysis of ERCC1 protein representation in formalin-fixed paraffin-embedded (FFPE) tumor biopsies obtained during diagnostic endoscopy was established at our department on a weekly routine basis." (PMID 24817012, 2014). "Our study does not corroborate these results based on our blinded categorization of high- and low-intensity ERCC1 labeling of resected tumor tissue and analysis of association between ERCC1 expression and patient outcomes." (PMID 25191856, 2014). "It has been reported that the gene polymorphism of ERCC1 at codon 118 was a predictive factor for the tumor response to oxaliplatin/5-FU combination chemotherapy in patients with advanced CRC." (PMID 25175730, 2014). "By extension, A allele would be required to maintain normal levels of ERCC1, thus conditioning tumor malignancy and response to treatment." (PMID 25540025, 2014). "ERCC1 19442C>A was also associated with tumour response rate in univariate analysis (C/C, 46.7% vs C/A, 55.3% vs A/A, 87.5%) (Fisher’s exact test, P=0.093; trend test, P=0.048)." (PMID 21364592, 2011). "The results suggested that besides clinical features such as tumor stage and chemotherapy or radiotherapy treatment, polymorphisms of ERCC1 Asn118Asn and XRCC1 Arg399Gln were associated with survival of patients." (PMID 20003463, 2009). "In the univariate analysis of OS, low TP and ERCC1 expression in the tumour was associated with longer OS." (PMID 19127259, 2009). "In patients given cisplatin-based regimens as first-line chemotherapy, low ERCC1 mRNA expression alone correlated with a better tumour response, confirming a previously reported association." (PMID 18231104, 2008). "Therefore, we used this criterion and identified four tumors with mutations in ERCC4, one tumor with mutation in ERCC1, two tumors with mutations in FANCD2 of which one also had a mutation in ERCC4 and one sample with a mutation in SPRTN." (PMID 38260495, 2024). "There is evidence to support a certain predictive effect of ERCC1 and tumor susceptibility." (PMID 36277013, 2022). "Furthermore, NSCLC tumour tissue samples were detected to confirm the relationship between ERCC1 rs3212986 polymorphism and cisplatin sensitivity." (PMID 36181289, 2022). "Furthermore, not only the expression level of ERCC1 can regulate the response of tumor cells to cisplatin, but ERCC1 gene polymorphisms have also been proved to make sense." (PMID 34746001, 2021). "We recently demonstrated that CTCs detected after NACT were associated with tumour stem cell characteristics as well as ERCC1 expression which may also suggest a potential selection of this CTC subset by chemotherapy." (PMID 32558176, 2020). "The association of ERCC1 with immunotherapy response was analysed, assuming that ineffective ERCC1 increases defects in the DNA of tumor cells and causes stronger immune response to the tumor." (PMID 31521181, 2019). "Low ERCC1 transcript was linked to genomically unstable intClust. phenotype whereas high ERCC1 was associated with chromosomally stable intClust. and 8 tumours." (PMID 31405143, 2019). "In ER+ tumours, low ERCC1 protein was linked to poor disease relapse free survival (p = 0.044)." (PMID 31405143, 2019). "However, in ER− tumours that received adjuvant chemotherapy, low ERCC1 was associated with a reduced DRR compared to high ERCC1 (p = 0.001)." (PMID 31405143, 2019). "With both Ki67 and ERCC1 highly expressed, and the patients having both high risk of tumor proliferation and resistance to treatment, the risk of adverse prognosis may increase significantly." (PMID 29179456, 2017). "High ERCC1 expression was strongly associated with the presence of genomic alterations and expression levels increased with the number of deletions present in the tumor." (PMID 28747165, 2017).
tumor (continued). "In this study, we analyzed genotypes of VEGF-A, KDR, Flt4, PDGFRα, HIF-1α and ERCC1 in TETs, aiming to verify whether they correlate with increased tumor risk and/or with the outcome of these patients." (PMID 26254278, 2015). "TTF-1, Bcl-2, and ERCC1 were closely associated with tumor stage (P < 0.05)." (PMID 24667263, 2014). "Consequently, lower ERCC1 mRNA levels have been found consistently associated with an improved tumor response using platinum-containing compounds." (PMID 25253066, 2014). "c-erb-B2, EGFR, mTOR, ERCC1 overexpression levels, and loss of p27 may play roles in hepatocarcinogenesis and may be significant predictors of aggressive tumor behavior." (PMID 23162604, 2012). "In conclusion, c-erb-B2, EGFR, mTOR, and ERCC1 overexpression and p27 loss may play roles in hepatocarcinogenesis and may be significant predictors of aggressive tumor behavior." (PMID 23162604, 2012). "One proposed mechanism for ERCC1 in cancer development might be due to the aberrant expression of ERCC1 causing the dysfunction of DNA-repair capacity, leading to the accumulation of genetic damage, which might induce the emergence of an aggressive tumor phenotype." (PMID 36713431, 2022). "Thus, with the identification of both a BRCA2 mutation and ERCC1 negativity, this case clearly demonstrates the benefit of molecular profiling in optimising therapy for this rare tumour and avoiding aggressive protocols from which the patient was unlikely to derive benefit." (PMID 27488020, 2016). "Although the correlation between EGFR mutation and ERCC1 has been unclear, it can be postulated that an impaired capacity for DNA repair and synthesis may be correlated with increased genome instability and tumor mutations." (PMID 23940741, 2013). "In the second sample, ERCC1-19q13 counts were in the diploid range, while those of CEN-2 were in the triploid range, suggesting that the low ratio observed for this specimen may be attributed to either loss of ERCC1-19q13 in a triploid tumor, or chromosome 2 aneusomy." (PMID 24144331, 2013). "The mRNA levels of ERCC1 may correlate with DNA repair capacity in various tissues, and also predict the response to chemotherapy (high ERCC1 levels have been associated with tumor growth and lower levels have been associated with improved disease response)." (PMID 16914027, 2006). "Consistent with the association between PRMT1/5 and the DDR signature, significant positive correlations between PRMT1/5 and ERCC1 mRNA expression levels were observed in primary tumor specimens from the TCGA cohort." (PMID 38826355, 2025). "XRCC1, XRCC3, ERCC1, and ERCC2 encode proteins crucial for the repair of DNA damage induced by ionizing radiation, directly affecting tumor cell radiosensitivity." (PMID 41463244, 2025). "This study identifies and characterizes ERCC1-iASPP, a novel chimeric RNA derived from the neighboring genes ERCC1 and iASPP, which exerts tumor-promoting functions via coding and non-coding mechanisms." (PMID 41298233, 2025). "The expression levels of the three genes of interest involved in the NER pathway (i.e., ERCC1, ERCC2, and ERCC5) were obtained from diagnostic FFPE tumor samples." (PMID 39735668, 2025). "On the other hand, the Excision Repair Cross-Complimenting Group 1 (ERCC1) plays a pivotal role in tumour cell DNA repair mechanisms, impacting the efficacy of DNA-damaging chemotherapy agents such as cisplatin." (PMID 39335211, 2024). "The tumor expression of ERCC1 was determined using immunohistochemistry, and the tumor expression of ERCC1-XPF was determined via a proximity ligation assay." (PMID 39339159, 2024). "To gain a deeper understanding of naringin's mechanism, we employed western blotting to analyse the protein expression related to the p38MAPK signaling pathway, specifically p38, phosphorylated p38 and ERCC1, in tumor cells." (PMID 38947385, 2024).
tumor (continued). "Immunohistochemical staining of the tumor tissue demonstrated strong expression of ERCC-1, MRP-2, and XIAP in most of the HOXB9 OE/SKOV3-injected group tumors compared with the control SKOV3-injected group tumors." (PMID 36674764, 2023). "ERCC1, one of the genes involved in the nucleotide excision repair pathway, plays a key role in maintaining genomic stability and preventing tumor development." (PMID 35637613, 2023). "It detects the mutation of tumor driver genes EGFR and KRAS and the expression of drug resistance proteins ERCC1 and RRM1, respectively." (PMID 37854320, 2023). "Post-CRT CEA levels had the most consistent association with tumor response, while cfDNA integrity index, MGMT promoter methylation, ERCC-1, miRNAs, and miRNA-related SNPs were identified as potential predictive markers." (PMID 36766755, 2023). "As an important factor involved in nucleotide excision repair, ERCC1 contributes to platinum resistance by repairing platinum-induced DNA damage in tumour cells." (PMID 35711974, 2022). "Actually, it is often difficult to obtain sufficient tumour tissues to quantify the expression of ERCC1 clinically." (PMID 36181289, 2022). "HCT116-Tet-on or COLO205-Tet-on tumors were subcutaneously injected into nude mice to generate HCT116-Tet-on-ERCC1 or COLO205-Tet-on-ERCC1 tumor-bearing mice." (PMID 36230725, 2022). "A close correlation was observed between increased ERCC1 expression and high tumor immune dysfunction and exclusion (TIDE) score as well as HRD." (PMID 36338712, 2022). "Considering the post‐transcriptional regulation of miR‐15a on ERCC1 mRNA, we further performed an immunohistochemical staining on clinical tumour tissues to determine the correlation between the expression of ERCC1 protein and miR‐15a." (PMID 36181289, 2022). "HER2 was mainly expressed in the nucleus, and positive expression was observed in 41 of 85 tumour samples, while ERCC1 expression was positive in 50 tumour samples." (PMID 35711974, 2022). "Further, we studied the correlation between ERCC1 expression and microsatellite instability (MSI), homologous recombination deficiency (HRD), and tumor mutational burden (TMB) in pan-cancer." (PMID 36338712, 2022). "Western blotting was performed to analyze the expression levels of PI3K, OPTN, Akt, p-Akt, Bcl-2, Bax, caspase-3, cleaved caspase-3, ERCC1 and β-actin in the xenograft tumor tissues of mice." (PMID 35672728, 2022). "Tumour presence and ERCC1 expression in tumours were confirmed by histopathological analysis by pathologists blinded to treatment received." (PMID 33931939, 2021). "PFKFB3 silencing has been observed to reduce the expression of Akt, pAkt, and ERCC1 with subsequent accumulation of DNA damage, tumor cell death, and reduced tumor growth." (PMID 34831136, 2021). "Within the irradiated group, we found downregulation of UNG, FEN1, PARP3, POLD, NTLH1, ERCC1 and MPG which are linked to increased DSBs, sensitivity to alkylating agents, impaired tumor growth and reduced EMT, DSB repair and mitotic progression." (PMID 34680264, 2021). "While both PARP1, XRCC4 and ERCC1 are related to tumor resistance and metastasis, the specific biological mechanism and the existence of a common mechanism of action between the three are unclear and need further study." (PMID 33184404, 2020). "One consequence of increased ERCC1/XPF expression is a narrowed therapeutic window for platinum efficacy where the amount of platinum required to inhibit tumor growth leads to dose-limiting toxicities." (PMID 32344513, 2020). "DNA excision repair protein 1 (ERCC-1), ERCC-2 gene polymorphisms, X-ray repair cross-complementing protein 1 (XRCC-1) polymorphisms seem to be associated with tumor response." (PMID 32197436, 2020). "Another limitation is the lack of reliable antibodies for protein expression analysis in paraffin tumor samples, which limits the validation of potential biomarkers (e.g., ERCC1 and CUL4A)." (PMID 32365979, 2020).
tumor (continued). "We found that a higher gene expression of ERCC1 was observed in tumor tissue as compared to pericarcinomatous tissue in OSCC patients." (PMID 33029487, 2020). "It is considered that the low expression of ERCC1 is a sign of high invasiveness of tumor, and the prognosis is often poor." (PMID 32419821, 2020). "When ERCC1 is overexpressed, the DNA repair ability of tumor cells increases and their sensitivity to platinum drugs decreases." (PMID 33014113, 2020). "Formalin destroys the mRNA, so tumor samples should be taken for ERCC1 analysis before fixation to avoid wrong evaluation of ERCC1 expression." (PMID 31521181, 2019). "Higher relative risk for death was associated with high ERCC1 expression (p < 0.001), higher TNM and ECOG (p < 0.001; p < 0.001, respectively), tumor enlargement (p < 0.001), positive lymph nodes (p < 0.001) and distant metastasis (p < 0.001)." (PMID 31521181, 2019). "So far, the altered DNA repair activity of the ERCC1 and ERCC2/XPD variants has been considered central for its association with tumor risk and cancer patient outcome." (PMID 30847299, 2019). "On the other hand, low grade, Ki67 negative, PAM50 Luminal A and Genufu ER+/HER− (low proliferation) were more common in tumours with high ERCC1 transcript (all p values < 0.0001)." (PMID 31405143, 2019). "Similar to the METABRIC data, in ER+ tumours, low levels of ERCC1 was associated with an increased distant relapse DRR compared to high levels of ERCC1 [p = 0.007)." (PMID 31405143, 2019). "Experimental evidence suggested that CDDP-resistant tumor cells correlated with high expression levels of ERCC1." (PMID 31450627, 2019). "Low ERCC1 transcript was also associated with Ki67 positivity, ER−, PAM50 Luminal B, Pam50 Her2, Pam50 basal and Genufu ER+/HER− (high proliferation) tumours." (PMID 31405143, 2019). "(ii) High sPD-L1 levels were related to residual tumor burden, reduced PFS and OS, whereas low levels of sPD-L2 were associated with platinum-resistance and the presence of CTCs, especially ERCC1+ CTCs." (PMID 31681568, 2019). "Parameter β4 evaluates how ERCC1 expression impacts cisplatin’s efficacy on tumor growth, as seen by comparing the cisplatin growth curves with corresponding vehicle growth curves." (PMID 31331301, 2019). "Inhibition of PFKFB3 induced downregulation of ERCC1 followed by accumulated DNA damage, resulting in G2/M arrest and tumor growth delay." (PMID 29559632, 2018). "The list of genes with stringently tumor-specific hypermethylation includes, for instance, ERCC1, MGMT, POLD1, and RBBP8/CtiP." (PMID 29445424, 2018). "In fact, early data indicated that low expression of ERCC1 or XPF was associated with increased sensitivity to cisplatin in both cell lines and tumor tissues." (PMID 30208165, 2018). "In conclusion, this study showed that PFKFB3 expression promotes HCC growth through the PFKFB3/AKT/ERCC1 signaling pathway to enhance the ability of DNA repair and its pro-tumor effects during glycolysis." (PMID 29559632, 2018). "As such, it is well-established that ERCC1 expression is altered in several tumor types, including lung, head and neck, and ovarian cancers, suggesting its potential use as a drug target or biomarker for response to platinum-based chemotherapy." (PMID 30400270, 2018). "Correlation of pre-treatment tumor mRNA expression with XPF and MUS81 protein expression, measured by IHC composite score, showed a statistically significant association between ERCC1 mRNA expression and XPF protein levels (P = 0.041) in the clinical samples." (PMID 29739952, 2018). "An immunohistochemistry assay demonstrated that apoptosis was increased in tumor cells and ERCC1 expression and cell proliferation (Ki67 as a marker) were decreased in the PFK15-treated tumors compared with the vehicle-treated tumors." (PMID 29559632, 2018). "TS and ERCC1 expression levels were examined in tumor tissues of the 77 patients using immunohistochemical staining." (PMID 28977913, 2017).
tumor (continued). "Based on this evidence, several clinical studies have been conducted with the aim of relating ERCC1 tumor levels with response to oxaliplatin, but these results are still controversial." (PMID 28767665, 2017). "Our results from this study show that BZA treatment is highly effective in reducing XRCC-1, ERCC-1 and survivin expression in tumor cells." (PMID 28978005, 2017). "It is convenient to detect Ki67 and ERCC1 expression levels in primary tumor tissues as biological prognostic indicators." (PMID 29179456, 2017). "In conclusion, we showed that ERCC1 expression patterns in pretreatment specimens predicted tumor response and survival in patients undergoing platinum-based chemotherapy to treat metastatic or recurrent uterine cervical cancer." (PMID 29390553, 2017). "ERCC1 SNP rs11615 in codon 118 reduces ERCC1 transcription and is correlated with patient survival and platinum-based chemotherapy TR in multiple tumor types." (PMID 28977987, 2017). "Despite these limitations, we have shown that the pretreatment ERCC1 level in tumor cells was related inversely to the outcomes of platinum-based chemotherapy in patients with metastatic or recurrent uterine cervical cancer." (PMID 29390553, 2017). "These values were used as division lines to classify tumor tissues as those with high and low TS and ERCC1 expression levels." (PMID 28977913, 2017). "Paraffin-embedded tumour samples were reviewed by a single pathologist and tested for immunohistochemistry (IHC) expression of Ki-67, ERCC1, Bcl-2, and Lin28a." (PMID 28955403, 2017). "Forty-seven (78.3%) out of 60 EPNEC patients and 70 (85.4%) out of 82 SCLC patients had tumours with high expression of ERCC1 (H-score ≥ 200) (p = 0.28)." (PMID 28955403, 2017). "We provide rationale to validate clinical utility of ERCC1+CTCs among large multicenter clinical trials and to further elucidate their functional and tumor biological significance." (PMID 28388557, 2017). "Our findings suggest that there was still large variation in both the laboratory procedures and the tumour specimens used for ERCC1 evaluation." (PMID 26775588, 2016). "We quantitatively detected the anticancer effect of DDP/VP-16, mRNA and protein expression of ERCC1/TOP2A in C57BL/6 mice with tumor and in human NSCLC A549 cells, as well as in RNAi A549 cells." (PMID 27895586, 2016). "ERCC1 is a DNA excision repair protein that recognizes and removes cisplatin-induced DNA adducts such that patients with ERCC1-negative tumours derive greater benefit from platinum-based chemotherapy." (PMID 27488020, 2016). "We evaluated the significance of RRM1 and ERCC1 expression to predict tumor response to gemcitabine plus platinum chemotherapy (GP) and survival in advanced UC." (PMID 26200905, 2015). "Subsequently, the same authors investigated the tumour specimens from the IALT-Bio study for ERCC1 expression using a fluorescence-based automated scoring system (AQUA)." (PMID 26663950, 2015). "Here, we evaluated the significance of RRM1 and ERCC1 to predict tumor response to gemcitabine plus platinum and survival in patients with advanced UC." (PMID 26200905, 2015). "The sensitivity of tumor cells to taxanes can be enhanced by metformin via downregulation of p38MAPK-dependent ERCC1." (PMID 26510912, 2015). "Tumor cells contained appreciable quantities of ERCC1 protein, especially in the nucleus, whereas both tumor and stromal cells expressed DPD protein." (PMID 26372896, 2015). "Current data on the prognostic and predictive value of ERCC1 tumor immunoreactivity are inconsistent." (PMID 24817012, 2014). "We found that patients with low ERCC1 expression showed a significantly higher rate of good tumor response, and the adjusted OR (95% CI) was 2.16(1.32-3.45)." (PMID 25674147, 2014).